CDK4 (cyclin dependent kinase 4)
Diseases named in the same sentence as CDK4 in open-access papers (continued):
Sharing a sentence is not in itself a finding about the gene and the disease.
cancer (continued). "Given the recent finding that 11q13 amplification does not sensitize cancers to CDK4/6 inhibitor, SHANK2 may present an alternative target for treating cancers with 11q13 amplification." (PMID 32661924, 2021). "However, the efficacy of CDK4/6 inhibitor to HCC and other cancers are very limited." (PMID 34335258, 2021). "It was shown that PZH’s anti-cancer activities might be related to the suppression of STAT3 signaling pathways, therefore resulting in the upregulation of Bax/Bcl-2 ratios as well as down-regulation of CCND1 and CDK4 expression." (PMID 33658028, 2021). "However, aberrant CDK4 activation in Kras-mutant mesenchymal-like cancer cells can occur in a cell-autonomous manner, without being coupled with extrinsic signals or the MAPK pathway." (PMID 34309585, 2021). "In addition, CDC20, CDK4, MCM6, MAD2L1, MCM2 and MCM5 were leading genes intersecting in these four pathways, and a positive correlation between mRNA expression and LACTB was observed in most normal and cancer tissues." (PMID 33507917, 2021). "Interestingly, not only autophagy modulators, but also cell-cycle blockers (including CDK4/6 inhibitors) are able to induce cellular senescence in normal and cancer cells." (PMID 35008317, 2021). "Moreover, PZH has been found to block the G1/S cell cycle progression and to suppress both mRNA and protein levels of CCND1 and CDK4 in Caco-2 CRC cells, suggesting that inhibition of cell proliferation via cell cycle arrest is a potential MOA through which PZH exerts its anti-cancer effecs." (PMID 33658028, 2021). "However, combined usage of the CDK4/6 inhibitor palbociclib and the autophagy inhibitor HCQ results in growth arrest, accumulation of reactive oxygen species, and cellular senescence in cancers with an intact G1/S transition." (PMID 35008317, 2021). "Additionally, the expression of p16, which is known as intracellular CDK4 and CDK6 inhibitor, was downregulated in five out of eight cancer cell lines after combination treatment, but might be triggered mainly by IR." (PMID 34722291, 2021). "In addition, FDA-approved CDK4/CDK6 inhibitors, including ribociclib, abemaciclib, and palbociclib, as well as other CDK antagonists, are presently in clinical trials as single agents or combined with other drugs for various cancer types." (PMID 34361615, 2021). "Nevertheless, we identified the CDK4/6 inhibition axis as a potential correlate of response in mUC and RCC tumors treated with atezolizumab, suggesting that subsets of tumors may share mechanisms of response and resistance to cancer immunotherapy." (PMID 34172722, 2021). "Therefore, CDK4 could be regarded as a clinical prognostic marker for HCC progression and it could be inferred that expressions of CDK4 were essential for certain cancer progress." (PMID 33009370, 2020). "However, in luminal B cancers, where the amplicon is more often present, E2F1 programs, dependent on CDK4/cyclin D activation, may substitute for ER programs, which have lower activity in these cancers." (PMID 32987805, 2020). "Currently, all three CDK4/6 inhibitors are approved (in combination with aromatase inhibitors) for the treatment of estrogen receptor-positive/HER2-negative metastatic breast cancer, and many clinical trials using these drugs are in progress for other types of cancer." (PMID 32344731, 2020).
cancer (continued). "The effects of HA on cancer cells may be mediated through its receptor CD44, which triggers a cascade of signal transduction increases, including increases in PI3K, Cyclin D1 and CDK4." (PMID 32517712, 2020). "Therefore, it is not surprising that PARPi and CDK4/6i combinations are highly effective in RB-proficient cancer cells." (PMID 32249776, 2020). "Recently, we reported that MPM cancer cells, characterized by the expression of Rb and cyclin D1 and negative for p16INK4a, were sensitive to the CDK4/6 inhibitor palbociclib, which induced a cell cycle blockade in the G0/G1 phase associated with cellular senescence." (PMID 32708306, 2020). "Therefore, we hypothesized that combined inhibition of CDK4/6 and CDK2 might inhibit overexpressed C-MYC and hTERT sequentially, thereby inducing senescence and preventing cancer progression." (PMID 33260316, 2020). "Additionally, CDK4 and CDK6 are known to be expressed by both cancer models." (PMID 31548560, 2019). "mTOR signaling may promote the survival of cancer cells via enhancing the expression of FANCD2, CHK1 and RRM2 through CDK4/6 while inhibiting ATM, revealing the potential mechanisms of the increased cancer cell growth and proliferation under stressful conditions." (PMID 31285446, 2019). "In addition, more recent findings have shown that the non-canonical targets of CDK4/6 activity are important in tumorigenesis, including cancer cell self-renewal, glucose metabolism, and metastasis." (PMID 30720718, 2019). "A link between the cell cycle effects of NEK9 silencing and CDK4 suppression was suggested by pharmacological studies in which the CDK4 inhibitors palbociclib and ribociclib also induced a G1‐phase cell cycle arrest and senescence in the NRAS‐ and KRAS‐mutant cancer cell lines." (PMID 29112787, 2018). "However, the anti-cancer effects of fascaplysin and its derivatives via CDK4 have not been fully studied." (PMID 28961193, 2017). "Moreover, the functions of CDK1/cyclin B1 in human cancer had not been properly elucidated similar to CDK4/CDK6/cyclin D. Multi-CDK inhibitors that target CDK1 are well-tolerated in cancer patients." (PMID 25914884, 2015). "Proteomic expression levels of Cdk1 and Cdk4 are closely correlated in human cancers but not normal cells and have been shown to spontaneously go up and down together from experiment to experiment in several human cancer cell lines." (PMID 21668989, 2011). "Whether or not Cdk1/Cdk4 co-expression remained constant in cancer cells dying as a result of exposure to PRGPRP was thus examined by Western blotting." (PMID 21668989, 2011). "However, it is unclear whether or not GLS1 is essential for the survival of senescent cancer cells induced by therapies such as CDK4/6i." (PMID 39695080, 2024). "Notably, SCLC is an RB1‐inactivated cancer that is not listed as a candidate for CDK4/6 inhibitors." (PMID 39136283, 2024). "However, overexpression of CDK4 did not affect the mRNA levels of TSC1 in these cancer cells." (PMID 38890443, 2024). "The inhibitors of cyclin-dependent kinases 4 and 6 (CDK4/6) are effective and routinely administered to treat advanced hormone receptor-positive, HER2-negative breast cancer, though CDK4/6 alterations are not a hallmark of these cancers and do not predict the effectiveness of this therapy." (PMID 38549846, 2024). "Some preclinical studies have suggested that CDK4/6i, namely palbociclib, can be a substrate for the ABCB1 and/or ABCG2 transporters, which could inclusively affect their ability to cross the blood–brain barrier and decrease anticancer efficacy in cancer cells overexpressing the ABCB1." (PMID 37835528, 2023). "Finally, the PROTACs may have been tried for anti-resistance based on the action mechanism of PROTAC and the non-enzymatic function of CDK4/6, which benefits cancer therapy." (PMID 38138549, 2023).
cancer (continued). "Finally, voruciclib, one of the CDK4/6i with anticancer effects, in combination with the BRAF inhibitor vemurafenib in advanced BRAF-mutant melanoma or with the proteasome inhibitor bortezomib in TNBC xenografts was found to antagonize ABCB1- and ABCG2-mediated multidrug resistance in cancer cells." (PMID 37835528, 2023). "The number of patients with luminal cancer receiving only chemotherapy as first-line therapy was relatively high, which is due to the fact that only recently has first-line treatment shifted toward hormonal therapy and CDK4/6 inhibitors, which were not available during the study period." (PMID 37178424, 2023). "A possible better strategy may be first to allow full attainment of the robust cytotoxic activity of paclitaxel alone to the mitotic cancer cell population before exposing the remaining cells to CDK4/6 inhibitors when non-mitotic paclitaxel killing mechanism still can occur." (PMID 36185294, 2022). "Redox-mediated activation of IRE1α and ATF6α may support dormant cancer cell survival, while activating PERK phosphorylates eukaryotic initiation factor 2α (eIF2α) and inhibiting its translation of cyclin-dependent kinases (CDK4), Cyclin D1/D3, leading to quiescence of dormant cancer cells." (PMID 34685686, 2021). "One explanation for varying perceptions could be different frames of reference; while providers may compare CDK4/6 inhibitor symptom burden to that of more toxic cancer treatments (e.g., cytotoxic chemotherapy), patients may not have the same experiences for comparison." (PMID 34165265, 2021). "Mechanistically, the functional consequences of CDK4/6 inhibition apart from cell cycle arrest in NSCLC are largely unknown; yet, metabolic reprogramming in response to palbociclib has revealed unique targetable vulnerabilities in several cancers including pancreatic, colorectal, and leukemia." (PMID 32624705, 2020). "Indeed, there is a strong rationale to evaluate CDK4 and 6 inhibitors in HR+/HER2+ BC, since CDK4 and 6 pathways have been reported to be involved in HER2-targeted therapy resistance, and the pharmacological inhibition of CDK4 and 6 was shown to restore cancer cell sensitivity to the HER2 blockade." (PMID 33182657, 2020). "Collectively, our findings supports the hypothesis that activation of the ATM/AKT/GSK-3β signaling pathway leading to CDK4/CDK6/cyclin D1 overexpression plays a key role in LDR-induced hormesis, and is responsible for the difference of hormesis induced by LDR in normal and cancer cells." (PMID 27708248, 2016). "Knockout cancer cell lines and murine models lacking CDK2 or CDK4/6 expression revealed that each of these kinases can independently drive cellular proliferation." (PMID 40282469, 2025). "We conducted centralized re‐analysis of these genes in all index individuals by extracting data from targeted sequencing of a 360‐cancer gene panel and found no PVs in CDKN2A nor CDK4, confirming the previous routine testing results." (PMID 40072281, 2025). "Beyond CDK4/6 inhibitors, very few other CDK inhibitors are currently being tested in cancer, and none in other diseases." (PMID 39800748, 2025). "Specifically, combination therapy of miR-143 and miR-506 downregulates the levels of cyclin-dependent kinases (CDK) 1, CDK4, and CDK6 and induces apoptosis in cancer cells, but it does not affect normal lung fibroblasts." (PMID 40248198, 2025). "However, patients with other cancer types may not benefit equally from CDK4/6i." (PMID 38424044, 2024). "This suggests that unlike in normal cells where CDK4/6 can rapidly compensate for pharmacologic inhibition of CDK2 to drive ongoing proliferation, this is not the case in CCNE1-amplified cancers." (PMID 38047585, 2024). "Interestingly, our results showed that the expression levels of CDK4, CDK6, and cyclin D1 in CRC cells were visually reduced after POLQ knockdown, which suggested that POLQ knockdown affects the cell cycle process and may be a potential factor in cancer therapy." (PMID 39520627, 2024).
cancer (continued). "Results showed that STK16 overexpression upregulated the expression levels of c-MYC, GLUT1, and CDK4 in c-MYC WT cancer cells, but not in c-MYC S452A cancer cells." (PMID 38622518, 2024). "However, CDK4/6 inhibitors are not cancer-specific and may affect also other proliferating cells." (PMID 36817127, 2023). "Patients with rare cancers more frequently had CDKN2A and BRAF genetic alterations compared to patients with non-rare cancers, leading to more matches with CDK4/6 inhibitors (14% vs. 4%; p ≤ 0.001) or BRAF inhibitors (9% vs. 1%; p ≤ 0.001)." (PMID 37046628, 2023). "Even though the ecDNA landscapes of the three cancer cell types were not the same, we identified several ecDNA hotspots, such as the oncogene MYC, CDK4 and CCND1 genomic loci." (PMID 37517066, 2023). "Cyclin E1 deletion emerged as the leading candidate suppressing cell proliferation in Rb-knockout cancer cells, corroborating that CDK2 activation drives cell-cycle entry in the absence of CDK4/6 activity." (PMID 38030655, 2023). "In this section, we would discuss pathways proved in other cancer types but not in LSCC, including PI3K signaling pathway, VEGF/VEGFR signaling, and CDK4/6 pathway." (PMID 36198685, 2022). "It has been shown that Nic induces downregulation of CDK2 and CDK4, but not CDK7, cyclin D2 or cyclin H in other cancer types." (PMID 36304150, 2022). "In this review, new insights were given about classical signaling pathways which have been proved in other cancer types but not in LSCC, including PI3K signaling pathway, VEGF/VEGFR signaling, and CDK4/6 pathway." (PMID 36198685, 2022). "Using combined pan-cancer studies, moderately positive correlations of CCT2 mRNA were found with MYC, CDK2, CDK4, CCNE1 but not CCND1 (slight negative correlation)." (PMID 33996588, 2021). "This development starts from non-selective CDK inhibitors to selective CDK4/CDK6 inhibitors, and these have been applied in clinical cancer treatment." (PMID 34361615, 2021). "Recently, there have been studies on CDK4 and CDK6, but the mechanism of CDK2 in cancer is relatively lacking." (PMID 34409029, 2021). "Integrating these three complementary and orthogonal methods, we identify CDK4 and XPO1 as potential therapeutic targets in this cancer, which has no known alterations in these genes." (PMID 27329820, 2016). "Unlike HepG2, this cell line was not derived from cancer cells, but rather from skeletal muscle of a 19 year-old healthy donor and a cell line developed by retroviral knock-in of the TERT and CDK4 genes." (PMID 26823999, 2016). "Of the four CDKs (CDK1, CDK2, CDK4 and CDK6), CDK4 and CDK6 are not required for the cell cycle of normal cells but are essential for driving the cell cycle progression in various types of cancer." (PMID 24765199, 2014). "One study examining CDK dependencies in RB-proficient cancer cell types identified a subset of cell lines that relied on Cyclin E–CDK2 complexes for RB phosphorylation, independent of CDK4/6 activity, as evidenced by their resistance to cell cycle arrest from targeted deletions of CDK4 and CDK6." (PMID 40282469, 2025). "Emerging non-canonical roles of CDK4 and CDK6 could be leveraged to counteract drug resistance in cancer treatment, improving patient outcomes." (PMID 39800748, 2025). "Notably, these correlations are conserved across human cancer cell lines, where CDK6 expression is positively correlated with CDK4 dependency scores, while showing strong negative correlation with CDK6 dependency scores." (PMID 39617889, 2024).
cancer (continued). "Indeed, p16INK4a-negative cancer cell lines show a higher positive correlation for MARS1 and CDK4 protein levels than p16INK4a-positive cancer cell lines." (PMID 35501376, 2022). "However, our data showed that CCND1, an important partner of CDK4/6, is not strongly correlated with HCC patient survival or anti-cancer drug response." (PMID 31349793, 2019). "It is important to note that all of the work reported here has been performed in cancer cell lines in vitro, and it is not known whether the senescence phenotypes induced by combined TNKS/CDK4 inhibition will behave similarly in vivo." (PMID 31891587, 2019). "For instance, we found that, while many proteins belong to the druggable categories, including several “star” molecules including PDGFRB, CDK4, and PI3KCA derived from cancer driver gene analyses, their elevated expressions are not correlated with poor survival." (PMID 29520031, 2018). "In the pan-cancer analysis, a decreased probability of overall survival (OS) and disease-specific survival (DSS) was found in amplified tumors in comparison with non-amplified ones, with EGFR, CDK4, MDM2, KRAS, and CCNE1-amplified tumors being those associated with a worse prognosis." (PMID 36980521, 2023). "Thus, treatment of cells with CDK4/6i creates a highly favorable cellular environment for viral genome replication and has even the ability to convert XVir-N-31 at very low MOI from a non-replicative into a replication-competent status in cancer cells." (PMID 35948546, 2022). "How normal cells proliferate without CDK4 and CDK6, two cancer-driving kinases, remains unclear." (PMID 33082317, 2020). "A second generation of CDK4/6 inhibitors with a broadened non-catalytic mechanism that also destabilizes cyclin D-CDK6-p21 complexes and complexes containing p27 may overcome resistance mechanisms and improve the efficacy of CDK4/6 inhibitors as anti-cancer therapeutics." (PMID 34099663, 2021). "Notably, an increased reliance on CDK2 may be a therapeutic vulnerability, suggesting an opportunity for CDK2 inhibitors in cancers that delete CDKN1B (although, unlike CDK4/6 inhibitors, CDK2 inhibitors have not yet been successful in the clinic due to high toxicity)." (PMID 33166394, 2020).